MTOR (mechanistic target of rapamycin kinase)
Diseases named in the same sentence as MTOR in open-access papers (continued):
Sharing a sentence is not in itself a finding about the gene and the disease.
tumor (continued). "Intravenous nab-sirolimus was shown in pre-clinical studies to have higher intra-tumoral drug accumulation, mTOR suppression, and tumor growth inhibition compared to its oral counterparts, such as sirolimus and everolimus." (PMID 37041531, 2023). "Combining mTOR inhibitors with other targeted agents has demonstrated enhanced anti-tumor effects and improved survival compared to single-agent treatments." (PMID 37834408, 2023). "Some studies have shown that the PI3K/AKT/mTOR pathway is a central signaling pathway that coordinates aerobic glycolysis and cell biosynthesis in malignant tumor cells." (PMID 37810976, 2023). "IL-8 derived from GCMSCs induces the expression of PD-L1 in GC cells through c-Myc regulated by the STAT3 and mTOR signaling pathways and inhibits the anti-tumor immune response." (PMID 37885883, 2023). "This suggests mTOR activation in the pre-treatment tumor biopsies from patients with a short time to progression." (PMID 37210417, 2023). "The AMPK/mTOR signaling pathway is involved in tumor cell proliferation, apoptosis, invasion, metastasis, and drug resistance." (PMID 36647780, 2023). "Our study reveals a novel functional region of BAP31, and an intrabody against it inhibits N-glycosylation of EpCAM, activates genes related to cytotoxic autophagy, and inhibits the PI3K-Akt-mTOR pathway, significantly inhibiting tumor proliferation." (PMID 37834237, 2023). "AMPK works in an opposite manner to the Akt pathway and negatively regulates the mTOR pathway, which has been correlated with tumor suppression." (PMID 38068999, 2023). "For now, it is important to incorporate what is currently known about CYP3A4, CYP3A5, CYP2C8, and ABCB1 into the assessment of a patient when the mTOR pathway is a desired target in treating a tumor." (PMID 37240915, 2023). "The potential relevance of the Akt- and mTOR pathways in VitD/VDR signaling is supported by reports in other tumor types." (PMID 36902107, 2023). "These triple combination therapy options can dysregulate the PI3K/Akt/mTOR pathway, resulting in an intense anti-tumor effect against radioresistant OSCC cells." (PMID 38170015, 2023). "Of note, PD-L1 stimulation is a critical basis of the tumor cell glycolysis, and PD-L1 intervention impairs the tumor glycolysis through the mTOR cascade and glycolysis enzymes." (PMID 37828561, 2023). "The involvement of serine/threonine kinase AKT and mTOR in COX-2 regulated pro-tumor effects have been reported." (PMID 36818443, 2023). "These two amino acids, in turn, determine mTOR activation that is eventually responsible for tumor growth and invasiveness." (PMID 37781086, 2023). "Regarding SNHG26, it promotes cisplatin resistance in tumor cells by activating the AKT/mTOR signaling pathway." (PMID 37072493, 2023). "For instance, PD-L1 overexpression by tumor cells mediates Akt-mTOR activation, resulting in increased glucose uptake and glycolysis." (PMID 37020537, 2023). "The association of melatonin and rapamycin, an inhibitor of the Akt mammalian target of rapamycin (mTOR) signaling pathway, has a synergistic effect by reducing the toxicity of healthy cells and reducing the resistance of tumor cells against rapamycin." (PMID 37760056, 2023). "The mammalian/mechanistic target of rapamycin (mTOR) is a pivotal regulatory protein kinase involved in multiple tumor signaling pathways and plays an important role in cell growth, proliferation, angiogenesis, protein synthesis, and cell apoptosis." (PMID 38057772, 2023). "Increased expression of lncRNA CASC9 promoted tumor progression by suppressing autophagy-mediated cell apoptosis via the AKT/mTOR pathway." (PMID 36739404, 2023).
tumor (continued). "Everolimus is an mTOR inhibitor, which is believed to inactivate the mTOR pathway dependent by the merlin loss of function, while erlotinib is an oral EGFR-Ras-ERK inhibitor, targeting the tumor proliferation." (PMID 37741837, 2023). "Phosphoinositide 3-kinase (PI3K)/protein kinase B (AKT)/mammalian target of rapamycin (mTOR) signaling was upregulated after ionizing radiation (IR) exposure, which promotes tumor cell survival." (PMID 37802999, 2023). "NPT-BEZ235, a dual inhibitor of PI3K and mTOR, increased ciliogenesis of VHL-deficient hTERT-PRE1 cells and reduced tumor burden in a mouse xenograft model of RCC." (PMID 37780208, 2023). "Therapeutical strategies targeting the NLRP3 inflammasome in OC involve the use of Oridonin, which, through the suppression of the mTOR pathway, arrests OC spread, and Tranilast, which enhances the sensitivity of tumor cells to Cisplatin." (PMID 37891577, 2023). "Benzopyrone is the basic structure of Coumarins, inhibits carbonic anhydrase, targets PI3K/AKT/MTOR signaling pathways, induces cell apoptosis protein activation, and inhibits tumor multidrug resistance and microtubule polymerization." (PMID 37985782, 2023). "Potential biomarkers are identified by analyzing the genetic profile of the tumor, which can indicate the activation status of the mTOR pathway and predict the patient’s response to treatment." (PMID 37834408, 2023). "In the past NF2 has been described as a tumor suppressor gene by inhibiting PI3K/AKT/mTOR signaling." (PMID 37917191, 2023). "Overall, these results demonstrated that rhein effectively inhibited OC tumor growth through the mTOR pathway in vivo and has the potential to be used as a chemotherapeutic agent for OC." (PMID 37239855, 2023). "A previous study of CX-5461 on human OS in vitro found that CX-5461 induced anti-tumour activity via the activation of autophagy involving the mammalian target of rapamycin (mTOR) signalling pathways in the OS cell lines U-2-OS and MNNG/HOS." (PMID 37189750, 2023). "In this context it has been shown that vismodegib synergized well with BEZ235, a PI3K/mTOR dual inhibitor, to delay tumor growth both in vivo and in vitro." (PMID 37568705, 2023). "Combining these agents with mTOR inhibitors can lead to increased DNA damage and cell death in tumor cells." (PMID 37834408, 2023). "Recently published work suggested that the enzymatic function of PSMA is cleaving glutamate, thereby activating the glutamate-driven phosphoinositide 3-kinase and subsequently the mTOR pathway, leading to tumor cell survival and growth." (PMID 37569712, 2023). "FBXW7, a tumour suppressor, can recognize the substrates, namely, Cyclin E, c-Myc, Mcl, mTOR, Jun, and NOTCH, for the component of the SCF E3 ubiquitin ligase." (PMID 36936374, 2023). "The Hippo tumor-suppressive and mTOR prooncogenic signaling pathways are crucial cell-signaling cascades regulated by merlin." (PMID 37180489, 2023). "According to multiple logistic regression analysis, membranous WNT-1 was found to be negatively associated with a high-grade tumor, and cytoplasmic WNT-1 and nuclear mTOR were found to be positively associated with a high-grade tumor (p < 0.0001)." (PMID 37176048, 2023). "Proprotein convertase subtilisin/kexin type 9 (PCSK9) and HMG-CoA reductase (HMGCR), both significantly high expressed in CRC tumor as ezetimibe potential targets, also confirmed of tight correlation to mTOR." (PMID 36843944, 2023). "Selective inhibition of P13K/AKT/mTOR in TAMs can decrease pro‐tumor macrophages and increase M1‐type macrophages." (PMID 36794651, 2023). "The dual role of mTORC1 in tumor metabolism and growth requires further consideration, especially in patients treated with mTOR inhibitors." (PMID 37049920, 2023). "The expression of p-P3K, p-AKT, and p-mTOR in tumor tissues from xenograft mice was determined in the cytoplasm and nucleus of tumor cells." (PMID 37370314, 2023).
tumor (continued). "Based on the results of GSEA, while The PI3K/AKT/mTOR signaling pathway has multiple functions in the regulation of various biological behaviors in tumor cells and plays a crucial role in the occurrence and development of NSCLC." (PMID 37974250, 2023). "Cell-based and in vivo research showed that mTOR inhibitors can enhance the efficacy of various tumor immunotherapy methods by elevating PD-L1 expression in tumor cells and inhibiting the activation of T memory cells." (PMID 38057772, 2023). "The mammalian target of rapamycin (mTOR) kinase, a central component of the PI3K/AKT/mTOR pathway, plays a critical role in tumor biology as an attractive therapeutic target." (PMID 38057772, 2023). "Based on the results of GSEA, while PI3K/AKT/mTOR signaling pathway also has multiple functions in the regulation of various biological behaviors in tumor cells and plays a crucial role in the occurrence and development of NSCLC." (PMID 37974250, 2023). "PI3K/AKT/mTOR is one of the effective intracellular axes in regulating growth, metabolism, motility, and cell proliferation of tumor cells." (PMID 37576045, 2023). "A trial of BKM120 (buparlisib), a small-molecule inhibitor of the PI3K signaling pathway, demonstrated inhibition of the PI3K/AKT/mTOR signaling, which is often overactive in tumor cells." (PMID 37524847, 2023). "AZD8055-mediated mTOR blockade efficiently delayed tumor growth resulting in prolonged tumor-specific survival, in agreement with the observed tumoristasis in AZD8055-treated KEP tumors." (PMID 37642941, 2023). "Since many different tumors, including renal and breast carcinoma, induce mTOR dysregulation, the disruption of this pathway can inhibit tumor growth and sometimes even lead to tumor regression." (PMID 37887285, 2023). "mTOR signaling cascade is constitutively active in tumors to aid in tumor cell proliferation, growth, and metabolic activity." (PMID 37204251, 2023). "Dysregulation of the mTOR signaling cascade has been identified in numerous tumors, including MM, leading to uncontrolled tumor growth and survival." (PMID 37190302, 2023). "For example, DDR1 is highly expressed in GBM and leads to the resistance of tumor cells to radiotherapy and chemotherapy by affecting the Akt and mTOR signaling pathways." (PMID 37031216, 2023). "Our previous work has established inhibition of PI3K/AKT and mTOR activation in PDAC by Uro A reduces tumor growth and significantly improves overall survival in the PKT GEMM of PDAC." (PMID 37448553, 2023). "The AKT/mTOR signaling pathway is the main pathway regulating autophagy, which determines the survival and death of tumor cells and plays a crucial role in tumorigenesis." (PMID 37138336, 2023). "In normal cells, the mTOR signaling pathway is an important regulator of cell growth and division, but in tumor cells abnormal activation of this pathway encourages tumor cells to grow, invade healthy tissues, and metastasize." (PMID 37511619, 2023). "PGAM1 regulates Hypoxia-inducible factor 1α (HIF-1α) and PI3K/Akt/mTOR pathways that in turn can provide required energy for proliferation, invasion, and metastasis of tumor cells." (PMID 37501157, 2023). "In tumor M-MDSCs with high glycolytic rates, several signaling pathways were downregulated, but the upregulation of phosphor-mTOR has been depicted as the main difference between tumor M-MDSCs and splenic M-MDSC." (PMID 37895302, 2023). "By contrast, the combined treatment of cisplatin and baicalein exerted anti-tumor effects through inhibition of the phosphorylation of Akt, mTOR and Erk, and the expression of Bcl-2." (PMID 37940982, 2023).
tumor (continued). "At the same time, this study also verified that BV facilitated the increase of IL8 and VEGF secretion by activating the PI3K/AKT/mTOR signaling pathway in tumor." (PMID 36732757, 2023). "The phosphatidylinositol PI3K/AKT/mTOR pathway is a critical survival pathway for cell proliferation, apoptosis, autophagy and translation in neoplasms." (PMID 36911388, 2023). "An interrogation of primary BlCa tumor transcript data (cBioportal, 413 samples) uncovered a strong statistical correlation between AR and mTOR expression, supporting our results linking AR and mTOR." (PMID 36720985, 2023). "Being a master regulator of cellular metabolism dysregulation of the P13K/Akt/mTOR signalling pathway contributes to several pathological conditions, including tumour progression, maintenance and metastasis." (PMID 36826068, 2023). "It is well known that PI3K/AKT/mTOR is a classic pathway during tumorigenesis and development, and its excessive activation is closely related to the malignant behaviours of tumours such as invasion, metastasis and proliferation." (PMID 38223571, 2023). "Nevertheless, downregulation of AKT and mTOR in these tumor cells is transient, since mTOR downregulation leads to FOXO de-repression, and consequently, RTK transcription, resulting in PI3K p110α-induced AKT signal transduction cascade." (PMID 37596643, 2023). "As a result of the interaction of MM cells with stromal cells, IL-6, VEGF, and IGF-1 are secreted, and signaling pathways that cause tumor aggression, such as PI3K/AKT/mTOR, MEK/ERK, JAK/STAT3, and NF-κB, are activated." (PMID 38239705, 2023). "SSN2 plays a tumour suppressive role by the inhibition of tumour growth and the activation of autophagy process, regulating the mTOR/AMPK signalling pathway." (PMID 36998446, 2023). "A phase ІІ clinical trial study on 25 patients with advanced HCC showed rapamycin exerts anti‐tumor effects by inhibiting mTOR and inducing autophagy." (PMID 36760166, 2023). "The PI3K/AKT/mTOR signaling pathway is closely related to tumor survival, proliferation, and distant metastasis." (PMID 37371816, 2023). "Salmonella was found to downregulate HIF-1α expression via downregulation of the AKT/mTOR pathway, which in turn inhibited tumor VEGF expression and angiogenic signaling." (PMID 37765183, 2023). "Scientists found that inhibition of HSP90 with the IPI-504 adjuvant, together with mTOR inhibition via Rapamycin, results in cell death and tumor regression in murine models." (PMID 36899885, 2023). "TFE3 enables tumor cells to obtain sufficient energy by activating the autophagy and mTOR signaling pathways." (PMID 36906611, 2023). "In different studies, miR-10a showed a tumor-suppressive function targeting the PI3K/Akt/mTOR signaling pathway." (PMID 37893081, 2023). "The regulatory roles of MYC, mTOR, and E2F in tumor initiation and progression processes are widely recognized." (PMID 37759234, 2023). "The mammalian target of rapamycin (mTOR) signaling pathway plays a critical role in tumor metabolism by regulating cell proliferation, autophagy, and apoptosis." (PMID 36831355, 2023). "Recent studies have shown that MELK contributes to tumorigenesis and tumor progression through activation of the PI3K/mTOR cascade." (PMID 37949877, 2023). "Meanwhile, the phosphorylation level of mTOR is a tumor marker of CRC and an important regulatory protein in the PI3K/Akt/mTOR signaling pathway, which mainly regulates cell survival, proliferation and apoptosis, and other physiological functions." (PMID 36768602, 2023). "The mTOR pathway can also promote tumor angiogenesis through inducing the transformation of tumor-associated macrophages (TAM) into M2-type." (PMID 36865794, 2023). "There are only few studies available that have investigated tumour heterogeneity in the mTOR pathway in GEP-NENs." (PMID 36980746, 2023).
tumor (continued). "Tuberin forms a heterodimer with the protein product of TSC1, hamartin, which functions as a tumor suppressor by inhibiting the mTOR signaling pathway." (PMID 37041531, 2023). "With the application of anti-CTLA-4 or anti-PD-1 antibodies, the activity of glucose metabolism of T cells can be restored, and glycolysis in tumor cells can be suppressed by reducing the expression of mTOR and glycolysis-related genes." (PMID 37342333, 2023). "Because of mTOR involvement in the control of tumor progression, the mTOR inhibitors, aside from their well-established use as immune suppressants, have also been developed and approved in oncology indications." (PMID 37372982, 2023). "The TGF‐β and PI3K/AKT pathways can activate mTOR in tumor cells, regulate endothelial cell growth, and enhance the characteristics of tumor stem cells." (PMID 36994237, 2023). "Systemic PI3K/AKT/mTOR activation in tumor epithelia and stroma/immune cells was detected in patients with PD." (PMID 36797347, 2023). "On the other hand, nuclear mTOR can be used for the confirmation of grade 3 neoplasms, as it has higher specificity (77.5%) than WNT-1." (PMID 37176048, 2023). "The PI3K/AKT/mTOR signaling pathways play important roles in cell growth and survival, driving tumor proliferation and progression." (PMID 36861063, 2023). "It has been reported that SFN can inhibit resistance-related tumor dissemination during treatment of BC with everolimus, demonstrating great potential for treating BC patients who are resistant to mTOR inhibitors." (PMID 37781700, 2023). "Nevertheless, mTOR inhibitors also seem to inhibit the function of Treg cells, so more research is needed to find mTOR inhibitors that maximize the anti-tumor effect." (PMID 38264667, 2023). "The AMP-activated protein kinase (AMPK) and mammalian target of rapamycin (mTOR) pathways are essential for autophagic regulation in tumor cells." (PMID 37190065, 2023). "Due to the key role of mTOR on tumor metabolism, we suggest that impaired DU-145 cells proliferation by compound 11 is caused by a reduced mTOR expression (less mTOR protein) and inhibitory activity on mTOR protein." (PMID 37298798, 2023). "In human nasopharyngeal carcinoma xenografts, it was reported that Ang 1–7 can down-regulate PI3K/Akt/mTOR pathway and inhibit tumor growth via autophagy." (PMID 37891636, 2023). "Enhancing DDIT4 expression has been shown to be an effective strategy for inhibiting the growth of a variety of tumours by repressing mTOR activity and the phosphorylation of the downstream protein S6." (PMID 36681687, 2023). "A study in ovarian cancer mouse models reported that BGJ398 and rapamycin inhibition of FGFR and mTOR reduced tumor size and induced tumor regression, apoptosis, and cell cycle arrest in OC cells." (PMID 37626639, 2023). "In gastric signet-ring cell carcinoma, the deletion of the Estrogen Receptor beta gene promotes tumor invasiveness through the mTOR-Arpc1b/EVL signaling pathway, resulting in a higher T stage." (PMID 36983615, 2023). "The results obtained in this work showed a profound inhibition of tumor growth, which was associated with a reduction in cell proliferation, an increase in apoptosis, and a reduction in the MAPK and PI3K/AKT/mTOR signaling pathways." (PMID 38066554, 2023). "The phosphatase and tensin homolog (pTEN) is a potent inhibitor of PI3K/AKT/mTOR-mediated tumor suppression." (PMID 38068984, 2023). "Simultaneously, the activation of the mTOR signaling pathway can better use autophagy decomposition products to promote the synthesis of various substances for the metabolism of tumor cells." (PMID 36906611, 2023).